OR4K15 (olfactory receptor family 4 subfamily K member 15)
Description:
Odorant receptor.
Synonyms: OR4K15Q; OR14-20
Tractability: Small molecule: it belongs to a druggable protein family. Antibody: UniProt places it where antibodies can reach, with medium confidence; UniProt predicts a signal peptide or a membrane-spanning region; its Gene Ontology location is reachable by antibodies, with medium confidence.
Gene: Protein-coding gene on chromosome 14 (19,975,591 to 19,976,565, forward strand). Ensembl gene ENSG00000169488.
Subcellular location: Cell membrane
Pathways (Reactome):
Sensory Perception: Expression and translocation of olfactory receptors
Gene Ontology:
Molecular function: olfactory receptor activity; G protein-coupled receptor activity
Biological process: detection of chemical stimulus involved in sensory perception of smell; G protein-coupled receptor signaling pathway
Cellular component: plasma membrane; membrane
Genetic constraint (gnomAD): Loss-of-function variants: 0 observed, 0.95 expected, observed/expected ratio (o/e) 0, 90% interval 0 to 1.74. That is too few expected variants to judge how well the gene tolerates losing a copy. Missense variants: 392 observed, 398.05 expected, observed/expected ratio (o/e) 0.98, 90% interval 0.91 to 1.07. Synonymous variants: 144 observed, 149.12 expected, observed/expected ratio (o/e) 0.97, 90% interval 0.84 to 1.11.
Homologues: Orthologues: chimpanzee OR4K15 (99% identical), macaque OR4K15 (96% identical), dog OR4K15 (94% identical), mouse Or4k15 (94% identical), rat Or4k15 (89% identical), rabbit OR4K15 (87% identical), mouse Or4k15c (87% identical), rat Or4k15c (86% identical), mouse Or4k15b (85% identical). Paralogues in human: OR4K5 (67% identical), OR4K14 (64% identical), OR4K13 (63% identical), OR4K1 (60% identical), OR4K17 (60% identical), OR4K2 (59% identical), OR4L1 (56% identical), OR4F5 (56% identical), OR4F4 (55% identical), OR4F17 (54% identical), OR4F6 (54% identical), OR4E2 (51% identical), and 116 more.
Diseases named in the same sentence as OR4K15 in open-access papers:
OR4K15 is named in the same sentence as 4 diseases in open-access papers, as found by Europe PMC text mining. Sharing a sentence is not in itself a finding about the gene and the disease. The quoted sentences say what the papers report.
hypothyroidism (1 paper, 2022). Abnormally low levels of thyroid hormone. "On the other hand, upregulation of IFNA4 was only observed in neuropathy and hypothyroidism and expression of OR4k15 was increased significantly in neuropathy and PCOS as shown by Boxplots 8I and 8K, respectively (P < 0.01)." (PMID 36175575, 2022).
cancer (1 paper, 2019). A tumor composed of atypical neoplastic, often pleomorphic cells that invade other tissues. "Our results show that nsSNVs found in multiple cancer types are located within exomes of TNN, KIR2DL1, OR4K15, and ZNF99 genes." (PMID 30934003, 2019).
OR4K15 also shares sentences with these, for which no sentence is quoted: breast carcinoma (1 paper); neuropathy (1).